BPTF (bromodomain PHD finger transcription factor)
Diseases named in the same sentence as BPTF in open-access papers (continued):
Sharing a sentence is not in itself a finding about the gene and the disease.
bladder cancer (9 papers, 2013 to 2023). "Because WDR5 and BPTF are necessary for H2A.Z to upregulate gene transcription in the bladder cancer cells, we also check whether they are functionally linked to H2A.Z-induced cell growth." (PMID 24279307, 2013). "This includes Cdr1as, a circular RNA that mediates bladder cancer chemotherapeutic response via miR-1270 and circ-BPTF, which promotes recurrence through interaction with miR-31-5p." (PMID 36674480, 2023). "Circ-BPTF promotes bladder cancer progression and recurrence through miR-21-5p/RAB27A axis, while Circ_0008035 promotes gastric cancer cell proliferation and inhibits apoptosis through miR-599/EIF4A1 axis." (PMID 35444695, 2022). "In bladder cancer, H2A.Z nucleosomes are enriched for the active histone modification H3K4me2/me3, which facilitates to recruit BPTF to H2A.Z target genes." (PMID 34736517, 2021). "For instance, circ-BPTF accelerated the development of bladder cancer through up-regulating RAB27A via targeting miR-31-5p." (PMID 33005174, 2020). "Serving as a miR‐31‐5p sponge, circ‐BPTF might aggravate bladder cancer development." (PMID 36444635, 2022). "For example, a circular RNA (hsa_circ_0000799) derived from BPTF exons attenuates the anti-oncogenic effect of miR-31-5p and consequently enhances RAB27A expression in bladder cancer." (PMID 34736517, 2021). "We have shown that BPTF is required for cell proliferation of BL, PDAC and bladder cancer cells in vitro." (PMID 26729287, 2016). "Here, we show that expression of circ-BPTF is increased in bladder cancer (BCa) tissues and cell lines compared with noncancerous tissues and cell lines." (PMID 30103209, 2018).
lung carcinoma (9 papers, 2015 to 2025). "The addition of C620-0696 to BPTF overexpressing lung cancer cells resulted in cytotoxicity, suppression of c-Myc expression, and inhibition of migration and colony formation, indicating that targeting of BPTF can be further explored as a treatment strategy." (PMID 31769422, 2019). "Examination of patient tumor samples indicated that BPTF is a suppressor of lung cancer metastasis to the brain." (PMID 30558204, 2018). "The effect of BPTF on lung cancer growth was further proved by using BPTF shRNA in vitro and in vivo." (PMID 26418899, 2015). "In this study, we examined the effects of BPTF on lung cancer cell proliferation, apoptosis and cell cycle, and further identified the underlying molecular mechanisms in vitro and in vivo." (PMID 26418899, 2015). "BPTF knockdown by siRNA also upregulated the cell cycle inhibitors such as p21 and p18 but inhibited the expression of cyclin D, phospho-Rb and phospho-cdc2 in lung cancer cells." (PMID 26418899, 2015). "Moreover, BPTF knockdown by its specific shRNA inhibited lung cancer growth in vivo in the xenografts of A549 cells accompanied by the suppression of VEGF, p-Erk and p-Akt expression." (PMID 26418899, 2015). "Therefore, our data indicate that BPTF plays an essential role in cell growth and survival by targeting multiply signaling pathways in human lung cancers." (PMID 26418899, 2015). "In a previous study, our group identified the first BPTF bromodomain inhibitor, C620-0696, through protein expression abnormalities in the epigenetic dimension of lung cancer, and demonstrated its ability to inhibit the proliferation and migration of lung cancer cells." (PMID 36364261, 2022). "Furthermore, we detected BPTF-mediated effect on cell cycle in lung cancer A549 and H322 cells." (PMID 26418899, 2015).
pancreatic cancer (8 papers, 2016 to 2025). "In Pancreatic Cancer circPDK1 and circZNF91 act as prognostic indicators; high expression of circPDK1, which promotes glycolysis by modulating the miR-628-3p/BPTF axis, is associated with a poor prognosis." (PMID 41301888, 2025). "A reduction in BPTF levels impaired cell proliferation and sensitized pancreatic tumour cells to gemcitabine." (PMID 35326669, 2022). "BPTF, as a core subunit of the NURF chromatin-remodeling complex, is required for c-myc transcriptional activity, and the BPTF-c-myc axis is involved in cell growth in pancreatic cancer." (PMID 36068586, 2022). "Notably, BPTF is required for c-myc transcriptional activity, and the BPTF-c-myc axis is involved in cell growth in pancreatic cancer." (PMID 36068586, 2022). "The interaction between endogenous c-MYC and BPTF was validated in MIA PaCa-2 pancreas cancer cells, expressing high levels of both proteins, using the in situ proximity ligation assay (isPLA) and affinity-purified rabbit antibodies recognizing BPTF residues 913–942." (PMID 26729287, 2016). "For instance, hsa_circ_0057104, an alternative splicing isoform of PDHK1, modulates the miR-628-3p/BPTF axis and degrades BIN1, thereby enhancing the growth, metastasis, and glycolysis of pancreatic cancer cells." (PMID 38360682, 2024). "BPTF knockdown suppressed the proliferation of pancreatic cancer cells and delayed the development of c-MYC-driven pancreatic tumors." (PMID 31769422, 2019). "In summary, these data indicate that BPTF is necessary for the initiation and maintenance of c-MYC-driven pancreatic tumours." (PMID 26729287, 2016).
gastric cancer (7 papers, 2018 to 2026). A primary or metastatic malignant neoplasm involving the stomach. "BPTF has been shown to contribute to erlotinib resistance in gastric cancer by regulating the c-MYC/PLCG1/p-Erk axis." (PMID 41602481, 2026). "BPTF inhibitor increases gastric cancer response to Erlotinib by epigenetically regulating c‐MYC/PLCG1/pErk axis." (PMID 37863665, 2023). "According to our GSE54129 dataset, the expression level of BPTF was increased in gastric cancer and furthermore, BPTF formed DRLs with PPM1L, NKX6.3 and PIK3R3." (PMID 35421923, 2022). "BPTF targeting treatment combined with Erlotinib could be a promising therapeutic strategy bring benefits to gastric cancer patients." (PMID 37863665, 2023). "Among the top 10 DRGs for Chinese (GSE54129), six genes have been reported to be gastric cancer (GC) related (REG4, ANXA13, C7, ASS1, MSMB, CREB1) and the rest four were directly regulated by known gastric cancer genes in our GRNs, in which two genes are also cancer related (BPTF, CLCA1)." (PMID 29745833, 2018). "Based on dataset GSE54129, involving 111 gastric cancer and 21 normal mucosa samples, we identified four TFs including CREB1, BPTF, GATA6 and CEBPA with high DR value among top 1% DRGs." (PMID 35421923, 2022).
renal cell carcinoma (7 papers, 2021 to 2025). "In renal cell carcinoma, the transcription factor BPTF can enhance the glycolysis of cancer cells to drive the distant metastasis of renal cell carcinoma." (PMID 37582735, 2023). "The enhancer action of low levels of BPTF is weakened, leading to reduced activation of downstream enolase 2 and other glycolytic related enzymes, and ultimately, the glycolytic level of renal cell carcinoma is reduced and distant metastasis is inhibited." (PMID 37582735, 2023). "BPTF has been demonstrated to be an oncogene in various cancers, including renal cell carcinoma and glioma, through regulated glycolysis, metastasis, and proliferation." (PMID 36068586, 2022). "recently investigated the vital role of m6A modification and the METTL14/BPTF axis in the epigenetic and metabolic remodeling of metastasis of renal cell carcinoma, highlighting the BPTF inhibitor-AU1 as a key therapeutic candidate." (PMID 36505780, 2022). "In renal cell carcinoma (RCC), METTL14 downregulates the expression of bromodomain PHD finger transcription factor (BPTF) to attenuate the oncogenic transcriptome, glycolytic reprogramming, and distal lung metastasis." (PMID 38721006, 2024). "Low METTL3 expression in renal cell carcinoma (RCC) suggests a tumor suppressor role, while reduced METTL14 expression weakens m6A modification on tumor suppressor transcripts (e.g. BPTF and PTEN), thereby promoting cancer cell invasion and metastasis." (PMID 41446042, 2025).
lung adenocarcinoma (5 papers, 2015 to 2024). A carcinoma that arises from the lung and is characterized by the presence of malignant glandular epithelial cells. "The results showed that high expression of BPTF was negatively associated with the overall survival, indicating that BPTF predicted a poor prognosis in lung adenocarcinomas." (PMID 26418899, 2015). "N, clinical stage and BPTF expression were also associated with survival of the patients with lung adenocarcinomas based on Univariate analysis of Cox regression model." (PMID 26418899, 2015). "Lifetime of lung adenocarcinoma was associated with clinical stage and BPTF expression." (PMID 26418899, 2015). "In 75 lung adenocarcinoma specimens, BPTF and VEGF overexpression was correlated with lymph node metastasis and clinical stage." (PMID 36529788, 2022). "Then we detected the percentage of positive BPTF expression in lung adenocarcinoma tissue by immunohistochemistry assay on a tissue microarray of 75 cases with cancer tissues and adjacent nonmalignant lung tissues." (PMID 26418899, 2015). "Immunohistochemical assay for tumor tissue microarrays of lung tumor tissues showed that BPTF overexpression predicted a poor prognosis in the patients with lung adenocarcinomas." (PMID 26418899, 2015). "Furthermore, multivariate analysis revealed that the clinical stages and BPTF expression were the influencing factors to lifetime of lung adenocarcinomas." (PMID 26418899, 2015). "Similarly, we detected the expression of BPTF protein expression in 75 lung adenocarcinomas and found 71% of them were positive." (PMID 26418899, 2015). "To see whether BPTF played a vital role in human clinical samples, we analyzed the data from 75 cases with lung adenocarcinoma." (PMID 26418899, 2015). "We also assessed whether BPTF expression was correlated with the overall survival in lung adenocarcinoma." (PMID 26418899, 2015). "Four loci, 5p15.33 (TERT), 6p21.3 (BTNL2), 3q28 (TP63) and 17q24.2 (BPTF), previously shown to be strongly associated with overall lung adenocarcinoma risk in East Asians, were re-discovered as loci associated with a higher susceptibility to EGFR mutation-positive lung adenocarcinoma." (PMID 27501781, 2016). "And BPTF was reported to regulate the MAP kinase and PI3K pathways in lung adenocarcinoma and epithelial-mesenchymal transition in colorectal cancer." (PMID 36530982, 2022). "The expressions of BPTF, VEGF, CD144 and CD31 were detected in lung adenocarcinoma samples by immunofluorescence, Western blot and immunohistochemical staining." (PMID 36529788, 2022). "Compared with para-cancer tissues, BPTF, VEGF, CD144 and CD31 were highly expressed in lung adenocarcinoma." (PMID 36529788, 2022). "Here we showed that BPTF was specifically overexpressed in NSCLC cell lines and lung adenocarcinoma tissues." (PMID 26418899, 2015).
non-small cell lung carcinoma (5 papers, 2022 to 2024). A group of at least three distinct histological types of lung cancer, including non-small cell squamous cell carcinoma, adenocarcinoma, and large cell carcinoma. "The results showed that BPTF knockdown inhibited VEGF, CD31 and VE cadherin associated with tumor angiogenesis in non-small cell lung cancer." (PMID 36529788, 2022). "In order to further study the clinical significance of BPTF-targeted regulation of VEGF in non-small cell lung cancer, we collected 26 patients who received bevacizumab treatment from January 2018 to January 2021." (PMID 36529788, 2022). "Finally, BPTF overexpression was shown to predict poor prognosis in non-small cell lung cancer." (PMID 36530982, 2022). "In non-small cell lung cancer, BPTF positive regulation of VEGF, BPTF high expression can predict better efficacy of bevacizumab, while BPTF low expression can predict poor efficacy of bevacizumab." (PMID 36529788, 2022).
Alzheimer disease (4 papers, 2014 to 2022). A progressive, neurodegenerative disease characterized by loss of function and death of nerve cells in several areas of the brain leading to loss of cognitive function such as memory and language. "Among them, BPTF is a protein-coding gene, about which researchers in neurodegenerative diseases are extremely concerned (such as Alzheimer’s disease)." (PMID 36505780, 2022).
glioma (4 papers, 2022 to 2024). A benign or malignant brain and spinal cord tumor that arises from glial cells (astrocytes, oligodendrocytes, ependymal cells). "BPTF maintains the self-renewal potential of glioma stem cells by promoting the transcriptional activation of the MYC gene and its downstream targets." (PMID 36967443, 2023).
Intellectual disability (4 papers, 2020 to 2025). "Heterozygous loss of function variations of the BPTF gene is associated with delayed psychomotor development and intellectual disability, poor growth, small head size, dysmorphic facial features, and mild abnormalities of hands and feet." (PMID 37260775, 2023). "Mutations in BPTF have been found in patients with intellectual disability, speech delay, and microcephaly, while genetic inactivation of BPTF in Zebrafish leads to neurodevelopmental phenotypes." (PMID 33193727, 2020).
leukemia (4 papers, 2016 to 2025). A malignant (clonal) hematologic disorder, involving hematopoietic stem cells and characterized by the presence of primitive or atypical myeloid or lymphoid cells in the bone marrow and the blood. "Together, these findings underscore the critical oncogenic dependency of KAT6A-rearranged leukemia on BPTF and CBP/P300." (PMID 40830799, 2025). "BPTF was depleted in K/C-III leukemia cells using shRNA, and 2 × 105 cells were transplanted into recipient mice for secondary transplantation." (PMID 40830799, 2025). "BZ1, a BPTF-H4K16ac inhibitor, induces cell cycle arrest and suppresses leukemia cell proliferation but exhibits weaker efficacy than BPTF knockdown, highlighting the need for further optimization." (PMID 40830799, 2025). "Building on the inhibitory effects of BZ1 in KAT6A-rearranged leukemia cells, we evaluated the therapeutic potential of targeting BPTF in the K/C leukemia model." (PMID 40830799, 2025). "Disease monitoring revealed that BPTF knockdown significantly delayed leukemia progression compared to GFP-shRNA (shGFP) controls." (PMID 40830799, 2025). "To investigate the effects of BPTF inhibition on gene expression, we performed mRNA-seq on K/C-III leukemia cells following 6 and 12 h of BZ1 treatment." (PMID 40830799, 2025). "A six-hour BZ1 treatment of K/C-III leukemia cells led to reduced genome-wide occupancy of both BPTF and K/C-III at BPTF-bound promoter regions." (PMID 40830799, 2025). "Collectively, these results highlight the critical role of the NURF complex, via BPTF, in mediating the genomic targeting of KAT6A chimeras in leukemia cells." (PMID 40830799, 2025). "Analysis of key factors, including Pol II, H3K27ac, BPTF, K/C, and MLL, in K/C-III leukemia cells revealed that A485 treatment for 6 h significantly decreased chromatin accessibility, Pol II loading, and the recruitment of the KAT6A-NURF-MLL module at Nup153 and Hoxa cluster loci." (PMID 40830799, 2025). "Quantitative analysis showed a marked enrichment of HaloTag-positive leukemia cells in the shGFP group, which was nearly absent in the BPTF knockdown group." (PMID 40830799, 2025).
breast tumors (3 papers, 2017 to 2025). "The splicing factors PRPF4B and BUD31 and the transcription factor BPTF are essential for cancer cell migration, amplified in human primary breast tumors and associated with metastasis-free survival." (PMID 31278301, 2019). "This analysis revealed an increase in the expression of CD8 T cell, NK cell, macrophage and Treg cell markers, and immune cell cytokines in breast tumors with low levels of BPTF expression." (PMID 28969075, 2017). "Using the mouse tumor models we do not detect significant differences in NK cell abundance with BPTF KD, but differences in abundance are observed in human breast tumors with low BPTF expression." (PMID 28969075, 2017). "Conditional BPTF depletion in established mouse breast tumors enhances antitumor immunity, suggesting that inhibiting BPTF could provide a novel immunotherapy." (PMID 28969075, 2017). "To determine if BPTF suppression of the antitumor immune response could be conserved in human tumors, we monitored the immune cell composition from human breast tumor microarray data sets using the CIBERSORT algorithm." (PMID 28969075, 2017).
colorectal cancer (3 papers, 2018 to 2025). A primary or metastatic malignant neoplasm that affects the colon or rectum. "Colorectal cancer patients who had higher BPTF expression tended to have poor survival, which suggests BPTF promotes cancer progression." (PMID 30558204, 2018). "Higher BPTF expression levels have also been reported in hepatocellular and colorectal cancers." (PMID 36530982, 2022).
hepatocellular carcinoma (3 papers, 2022 to 2025). A malignant tumor that arises from hepatocytes. "Previous studies have shown that BPTF knockout also inhibits the growth and metastasis of HCC tumors in xenograft mouse models, and that BPTF may have the potential to be a new target for hepatocellular carcinoma therapy." (PMID 36505780, 2022). "Numerous studies have reported that BPTF could enhance self-renewal capacity of tumor-initiating cells (TIC) and cancer stem cells (CSC), thus promoting the progression and metastasis of malignancies, such as lung cancer and hepatocellular carcinoma (HCC)." (PMID 37794386, 2023).
lymph node metastasis (3 papers, 2015 to 2023). "The results showed that high expression of BPTF was associated with N (lymph node metastasis) and clinical staging factors (P < 0.05) according to Pearson chi-square test." (PMID 26418899, 2015). "We found the high expression of BPTF was associated with N (lymph node metastasis) and clinical staging factors." (PMID 26418899, 2015). "Therefore, it is possible that the association of BPTF with N ( lymph node metastasis) is through its effect on VEGF." (PMID 26418899, 2015). "In the TCGA‐STAD cohort, BPTF mRNA was subjected to upregulation in tumor tissues, and BPTF upregulation was correlated with advanced T stage (depth of tumor invasion), N stage (lymph node metastasis), and pathological TNM (pTNM) stage." (PMID 37863665, 2023).
ovarian carcinoma (3 papers, 2016 to 2025). A malignant neoplasm originating from the surface ovarian epithelium. "By contrast, N-MYC and L-MYC expression levels correlated with c-MYC expression signatures only in medulloblastoma and ovarian carcinoma, respectively, and in these tumours the signatures correlated negatively with BPTF expression levels." (PMID 26729287, 2016).
prostate carcinoma (3 papers, 2016 to 2025). A carcinoma that arises from epithelial cells of the prostate gland. "In summary, our findings establish BPTF as a critical regulator of AR activity by promoting chromatin accessibility and stabilizing the AR-FOXA1 complex, highlighting BPTF as a potential therapeutic target in prostate cancer." (PMID 41381516, 2025). "Here the authors show that BPTF is upregulated in prostate cancer cells, increases chromatin accessibility at Androgen Receptor (AR)-binding sites, and stabilizes the AR-FOXA1 complex." (PMID 41381516, 2025). "BPTF, the scaffolding subunit of the nucleosome remodeling factor (NURF) complex, has been implicated in the progression of several malignancies, but its role in prostate cancer (PCa) remains unclear." (PMID 41381516, 2025).